GFAP (glial fibrillary acidic protein)
Diseases named in the same sentence as GFAP in open-access papers (continued):
Sharing a sentence is not in itself a finding about the gene and the disease.
Alzheimer disease (continued). "Finger-prick neurofilament light and GFAP were significantly elevated after acute traumatic brain injury with non-significant group-level increases in dementia (91% having Alzheimer’s disease dementia)." (PMID 38903933, 2024). "Serum GFAP differentiated Alzheimer’s disease patients from control with an area under the curve (AUC) of 0.87 and from behavioural frontotemporal dementia with an AUC of 0.81, highlighting GFAP’s potential as a differential biomarker." (PMID 39554381, 2024). "By integrating GFAP within a multi-biomarker strategy, clinical practice can advance towards more precise and personalized management of Alzheimer’s disease." (PMID 39554381, 2024). "Ocular diseases with increased GFAP expression include macular degeneration, Alzheimer’s disease, multiple sclerosis, and retinal degeneration." (PMID 38607034, 2024). "This review will explore the potential of GFAP within such a panel, examining its role in early diagnosis, disease progression monitoring and its integration into clinical practice for Alzheimer’s disease management." (PMID 39554381, 2024). "In Alzheimer’s disease, astrocytes adopt a reactive phenotype, with upregulation of proteins such as GFAP, a key cytoskeletal component." (PMID 39596011, 2024). "Activated astrocytes, with high expression of GFAP, are found to surround amyloid plaques in Alzheimer’s disease." (PMID 37530894, 2024). "Among those with MCI, increased WMH volume was associated with higher age-residualized NfL, while increased GFAP concentration and p-tau217 concentration were associated with higher age-residualized NfL in participants with MCI and Alzheimer’s disease." (PMID 39403075, 2024). "Folate can also enter with FOLR1 into GFAP-positive astrocytes, and this process becomes important in abnormal conditions such as Alzheimer’s disease." (PMID 39337690, 2024). "This study explores the potential of GFAP as a blood-based biomarker for early Alzheimer’s disease diagnosis and monitoring of disease progression." (PMID 39554381, 2024). "Such an increase in injury-related GFAP fragments has been found in plasma shortly after a traumatic brain injury but also in plasma of patients with the neurodegenerative disorder Alzheimer’s disease (AD)." (PMID 39275164, 2024). "Cryptotanshinone (CPT) has shown anti-inflammatory and neuroprotective effects in mouse models of Alzheimer's disease (AD) by significantly reducing the expression of S100β, GFAP, COX-2, iNOS, and NFkBp6530." (PMID 38796623, 2024). "This study aimed to evaluate the use of serum neurofilament light chain (NfL) and glial fibrillary acidic protein (GFAP) in the diagnosis of Alzheimer’s disease (AD) and the differential diagnosis between AD and mild cognitive impairment (MCI)." (PMID 38352136, 2024). "Altogether, plasma P-tau181, GFAP and NfL seem to be feasible biomarkers to detect different Alzheimer's disease-related pathologies already in presymptomatic individuals." (PMID 36626935, 2023). "Plasma GFAP and Alzheimer’s disease (AD) cerebrospinal fluid (CSF) biomarkers were assessed by the single molecule array and the Lumipulse platforms, respectively." (PMID 37762278, 2023). "Of all 527 journals, the Journal of Alzheimer’s Disease contributed to the most total link strength for the publications on GFAP within the area of AD." (PMID 37829140, 2023). "Plasma GFAP began to increase 10 years before symptom onset, prior to P-tau181 and NfL, suggesting that GFAP is mirroring Alzheimer’s disease pathology upstream of tau phosphorylation and neurodegeneration." (PMID 36626935, 2023). "Here we assess the value of plasma amyloid-β1-42/1-40, phosphorylated-tau181 and glial fibrillary acidic protein to detect early Alzheimer’s disease pathology, accounting for confounding by genetic and early environmental factors." (PMID 36824390, 2023).
Alzheimer disease (continued). "The overexpression of GFAP is characteristic of reactive astrocytes in Alexander disease, Alzheimer’s disease, major depression, and other pathologies." (PMID 36661521, 2023). "We suggest that plasma P-tau181, GFAP and NfL are feasible biomarkers to detect different Alzheimer's disease-related pathologies already in presymptomatic individuals." (PMID 36626935, 2023). "The hippocampal GFAP expression also increased significantly in a Streptozotocin induced model of Alzheimer’s disease, indicating a correlation between neuronal damage and glial cell infiltration." (PMID 36823675, 2023). "Increased 11C-DED brain binding seems to be an earlier phenomenon in Alzheimer’s disease progression than increased plasma GFAP concentration." (PMID 37697307, 2023). "Elevated plasma GFAP has been reported to be a sensitive biomarker for tracking reactive astrogliosis and is positively correlated with amyloid-beta (Aβ) deposition in Alzheimer’s disease (AD)." (PMID 37932720, 2023). "Finally, age is the greatest risk factor for Alzheimer’s disease development, and aging has been shown to induce astrocyte senescence, a cellular state characterized by hypertrophy, secretion of pro-inflammatory proteins, and increased expression of GFAP and vimentin." (PMID 37533101, 2023). "Growing evidence supports the use of plasma levels of tau phosphorylated at threonine 181, amyloid-β, neurofilament light and glial fibrillary acidic protein as promising biomarkers for Alzheimer’s disease." (PMID 37180996, 2023). "Subsequently, serum and cerebrospinal fluid (CSF) of Alzheimer’s disease (AD), Multiple Sclerosis (MS) and control patients were analyzed with the established assay, and levels were compared to the commercial GFAP Simoa discovery kit." (PMID 37168256, 2023). "Our aim was to analyze the trends and hotspots on glial fibrillary acidic protein (GFAP) within the area of Alzheimer’s disease (AD) by using a bibliometric method, which is currently missing." (PMID 37829140, 2023). "Regarding the abnormal astroglia activation response as a pathological pathway involved in neurodegenerative diseases, the glial fibrillary acidic protein (GFAP) plasma biomarker has been studied in Alzheimer’s disease." (PMID 37762457, 2023). "Increased levels of GFAP in the cerebrospinal fluid have been detected in people with neurodegenerative diseases, including Alzheimer’s disease and Parkinson’s disease." (PMID 36430485, 2022). "The latest research shows that berberine significantly decreases the expression of GFAP in the Alzheimer’s disease mice hippocampus, indicating berberine inhibits the overexpression of astrocytes in Alzheimer’s disease mice." (PMID 35668943, 2022). "Overexpression of GFAP in Alzheimer's disease, Parkinson's disease, and healthy patients is correlated with myelin impairment, and astrogliosis can inhibit axonal regeneration." (PMID 35971662, 2022). "Detection of GFAP in human CSF or serum is a critical biomarker of neuropathology, contributing to diagnoses of Alzheimer’s disease (AD), Parkinson’s disease (PD), dementia with Lewy bodies (DLB), and frontotemporal lobar degeneration (FTLD)." (PMID 35890250, 2022). "We found that several of these markers colocalize with GFAP+ cells in post-mortem samples from people with Alzheimer’s disease." (PMID 35592112, 2022). "GFAP in cerebrospinal fluid is a biomarker of Alzheimer’s disease (AD), dementia with Lewy bodies, and frontotemporal dementia (FTD)." (PMID 35890250, 2022). "Earlier studies showed that GFAP antibodies were detected in the serum of patients with Alzheimer’s disease, cancers, and brain injury using ELISA." (PMID 34880859, 2021). "There are studies that have reported higher levels of CSF GFAP in Alzheimer’s disease patients compared to healthy control subjects, reflecting the astrocytosis and degeneration of astrocytes." (PMID 33578866, 2021).
Alzheimer disease (continued). "In conclusion, GFAP is an astroglial marker, and there are elevated levels of GFAP in the CSF of Alzheimer’s disease patients." (PMID 33578866, 2021). "A previous study showed the presence of serum GFAP antibodies in patients with Alzheimer’s disease and cancer using ELISA." (PMID 34880859, 2021). "GFAP is a recognized indicator of astrogliosis in neuropathological disorders such as Alzheimer’s disease." (PMID 33578866, 2021). "We assessed the ability of plasma GFAP to detect Alzheimer’s disease (AD) pathology in the form of AD-related amyloid-β (Aβ) pathology and conversion to AD dementia in a mild cognitive impairment (MCI) cohort." (PMID 33773595, 2021). "What are the levels of plasma glial fibrillary acidic protein (GFAP) throughout the Alzheimer disease (AD) continuum, and how do they compare with the levels of cerebrospinal fluid (CSF) GFAP?" (PMID 34661615, 2021). "Glial fibrillary acidic protein (GFAP), an astrocytic cytoskeletal protein, can be measured in blood samples, and has been associated with Alzheimer’s disease (AD)." (PMID 33431793, 2021). "Circulating GFAP has also shown promise as an Alzheimer’s disease (AD) biomarker in several recent studies." (PMID 33678186, 2021). "A recent study highlighted that GDF11 treatment reduced both mRNA and protein levels of GFAP and Iba1 in a mouse model of Alzheimer’s disease, suggesting a role of GDF11 in attenuation of neuroinflammation." (PMID 32365331, 2020). "In our previous meta-analysis of human hippocampus derived biopsies, we also observed that GFAP expression strongly correlated with Alzheimer’s disease (AD)." (PMID 32138778, 2020). "Like YKL-40, CSF levels of GFAP increase in conditions with astrogliosis, such as Alzheimer’s disease and MS." (PMID 30678707, 2019). "The high citrullination of GFAP and vimentin with the abnormal accumulation of citrullinated peptides has been detected in the hippocampus of patients with Alzheimer's disease (AD)." (PMID 31886309, 2019). "Upregulation of GFAP is a common finding in diverse brain disorders, including Alzheimer’s disease, Parkinson’s disease, and many other disorders characterized by clinically significant tissue damage." (PMID 29765022, 2018). "GFAP was identified as a highly susceptible substrate of PAD2, and abnormal accumulation of citrullinated GFAP (cit-GFAP) was found in neurodegenerative diseases, including Alzheimer’s disease and prion disease." (PMID 30071078, 2018). "NFAT4 expression in a mouse model of Alzheimer’s disease also exhibited extensive co-localization with activated astrocytes, increasing directly in proportion to the expression of GFAP." (PMID 30297999, 2018). "The deimination sites found within vimentin and GFAP corresponded to previously reported sites of deimination, respectively, in rheumatoid arthritis and in multiple sclerosis and Alzheimer's disease." (PMID 28626499, 2017). "In support of these data, previous studies found that a 30 kDa GFAP fragment generated by caspase 3 cleavage at a unique DLTD266 site was present in reactive astrocytes of the Alzheimer disease brain." (PMID 28700643, 2017). "Specifically, citrullinated GFAP is a characteristic feature in MS and Alzheimer’s disease, and MBP, a major component of myelin sheath structure, is profoundly over-citrullinated in MS." (PMID 26441823, 2015). "Caspase 3 activation and GFAP cleavage contribute to the damaged astrocytes in AD (Alzheimer's disease) brain." (PMID 24102621, 2013). "Here, for the first time, we present a comprehensive study of GFAP isoform expression in both wild-type and Alzheimer Disease (AD) mouse models." (PMID 22912745, 2012). "GFAP−/− astrocytes also fail to form a barrier-like structure around amyloid β (Aβ) deposits, suggesting a role for GFAP in the structural alterations of reactive astrocytes surrounding plaques in Alzheimer Disease (AD)." (PMID 22912745, 2012).
Alzheimer disease (continued). "We previously reported that GFAP+1 was expressed in astrocytes and in degenerating neurons in Alzheimer's disease brains." (PMID 19888461, 2009). "The four fold or more increase in GFAP expression observed in all models is consistent with the well established astrocytosis known to occur in the mouse model of Alzheimer's disease as well as the models of TSE disease." (PMID 17367538, 2007). "Conversely, GFAP levels may decrease during stressful conditions such as Parkinson's or Alzheimer's disease when harmful astrocytes secrete a factor that induces neurotoxicity." (PMID 41036445, 2025). "GSEA of GFAP revealed that Alzheimer’s disease, anting processing and presentation, cytokine–cytokine receptor interaction showed an overall upregulation trend; while notch signaling pathway, oxidative phosphorylation, and Parkinson’s disease were identified showing an overall downregulation trend." (PMID 41009659, 2025). "Astrocytic activation (GFAP) was pronounced in the olfactory bulb, brainstem, and hippocampus, and both microgliosis and astrogliosis were particularly prominent in elderly patients with Alzheimer’s disease or delirium." (PMID 41305454, 2025). "Given findings that glial fibrillary acidic protein (GFAP), an astrocytic cytoskeletal protein, shows promise as a biomarker for traumatic brain injury (TBI), Alzheimer disease and other diseases, we examined the potential utility of GFAP as a biomarker for FTD." (PMID 40075459, 2025). "Blood‐based phosphorylated tau 217 (p‐tau217), glial fibrillary acidic protein (GFAP), and neurofilament light chain (NfL) show promise for Alzheimer's disease (AD), while their links to brain amyloid beta (Aβ)/tau, hippocampal atrophy, and cognitive decline need further investigation." (PMID 41376134, 2025). "GFAP moderation of Alzheimer's disease (AD)‐related neurodegeneration and cognition is unclear." (PMID 40911721, 2025). "Assessing GFAP in CSF may provide more direct insights into central nervous system pathology than plasma and could improve the characterization of Alzheimer’s disease (AD) stages and support treatment monitoring." (PMID 40943059, 2025). "A GFAP immunoassay study on brain tissues revealed that the most pronounced glial response occurs in the hippocampus within the temporal lobe, the region where Alzheimer’s disease first induces neurological damage." (PMID 39554381, 2024). "In conjunction with GFAP, it labels reactive astrocytes and exerts neurotoxicity in neurodegenerative diseases, such as Alzheimer’s disease (AD), ALS, multiple sclerosis (MS), and Parkinson’s disease (PD), as well as in infectious diseases and spinal cord injury." (PMID 38391732, 2024). "Previous studies showed that the neuroprotective benefits of 17β-estradiol (E2) ameliorated cholinergic deficit, elevated the expression levels of choline acetyltransferase and 5-hydroxytryptamine receptor 2A, and lowered the expression of GFAP in a rat model of Alzheimer’s disease induced by OVX." (PMID 38732143, 2024). "Integrating GFAP into the existing ATN framework could enhance its ability to reflect the complex pathology of Alzheimer’s disease, providing valuable insights into the role of reactive astrogliosis in Alzheimer’s disease." (PMID 39554381, 2024). "NfL and GFAP are promising blood-based biomarkers for Alzheimer's disease." (PMID 37723371, 2024). "Although pTau and Aβ are the most commonly used blood biomarkers for assessing amyloid pathologies and tauopathies in Alzheimer’s disease, recent studies have identified GFAP as a reliable alternative and potentially more sensitive indicator of pathological states." (PMID 39554381, 2024). "Moreover, GFAP expression has been found to increase in the brains of patients suffering from Alzheimer’s disease." (PMID 37966585, 2024).
Alzheimer disease (continued). "In the context of neurodegenerative disorders, such as Alzheimer's disease (AD), the measurement of blood GFAP has demonstrated heightened efficacy compared to CSF levels in capturing amyloid-β (Aβ) pathology, particularly in the initial stages of the AD spectrum." (PMID 38668889, 2024). "These previous findings propose that GFAP BDPs are likely present in TBI, ALS, SCI, Alexander disease, and Alzheimer’s disease-associated biofluids; here, we suggest the presence of these truncated forms in the TEV population and ADEV subpopulation of IS patients." (PMID 38891912, 2024). "Additionally, GFAP both effectively distinguished Alzheimer’s disease from other neurodegenerative dementias, such as dementia with Lewy bodies (P < 0.001)." (PMID 39554381, 2024). "Previously, GFAP and MT3 have been linked to trauma, ischemia, and neurodegenerative diseases, including encephalomyelitis, multiple sclerosis, Parkinson’s disease, Alexander disease, Alzheimer’s disease, and amyotrophic lateral sclerosis." (PMID 38866016, 2024). "Interestingly, the increased GFAP expression in astrocytes may be indicative of reactive phenotype and morphological changes often associated with inflammatory conditions in neurological diseases, such as Alzheimer’s disease and amyotrophic lateral sclerosis (ALS)." (PMID 39605786, 2024). "GFAP levels have also been shown to be valuable in identifying Alzheimer’s disease (AD)." (PMID 39796043, 2024). "The reason plasma GFAP could serve as a promising biomarker for diagnosis and prediction of Alzheimer's disease (AD) is that it effectively distinguished AD dementia from multiple neurodegenerative diseases and predicted the individual risk of AD progression." (PMID 38216970, 2024). "Our results suggest that plasma GFAP might reflect Alzheimer's disease pathology upstream to accumulation of tangles and neurodegeneration." (PMID 36626935, 2023). "Notwithstanding, the fewer follow-up points for modelling the PET tracer binding than the plasma GFAP trajectories, the findings suggest that reactive brain astrogliosis measured with 11C-DED binding and plasma GFAP concentration reflect distinct aspects of the Alzheimer’s disease pathology." (PMID 37697307, 2023). "Our data support the use of amyloid-β1-42/1-40, phosphorylated-tau181 and glial fibrillary acidic protein as screening tools for Alzheimer’s disease pathology in the normal aging population, which is of importance for enrolment of high-risk subjects in secondary, or even primary, prevention trials." (PMID 36824390, 2023). "Lastly, patients with Alzheimer’s disease and cancer have been shown to have serum GFAP antibodies." (PMID 37350972, 2023). "Although JAK inhibition can have adverse side effects, strategies to specifically target STAT3 with small molecules have been effective in preclinical models of Alzheimer’s disease and may provide alternatives for reducing GFAP pathology in AxD." (PMID 37048051, 2023). "Thus, high plasma GFAP concentration was detected mainly in patients with Alzheimer’s disease dementia while high 11C-DED binding was detected mainly in presymptomatic ADAD mutation carriers and patients with MCI+." (PMID 37697307, 2023). "Visuospatial dysfunction or elevated plasma GFAP may signal a subgroup of RHI/TES patients with Alzheimer’s disease pathology contributing to their symptoms (i.e., Aβ[ +] RHI/TES)." (PMID 37480088, 2023). "Also in other neurodegenerative conditions such as Alzheimer ́s disease (AD), blood GFAP appears to be superior to CSF levels in terms of reflecting Aβ pathology, especially at the early stages of the AD continuum." (PMID 37314506, 2023). "Serum glial fibrillary acidic protein (GFAP), as an intermediate filament of mature astrocytes, associates with cognitive decline in neurological disorders such as Alzheimer’s disease, reflecting disease-related reactive astrogliosis and astroglial damage in the brain." (PMID 36142218, 2022).